PPARA (peroxisome proliferator activated receptor alpha)
Diseases named in the same sentence as PPARA in open-access papers (continued):
Sharing a sentence is not in itself a finding about the gene and the disease.
tumor (continued). "Our observation that blocking PPARα restored DCs immune function in vitro prompted us to examine whether PPARα blockade decreased the lipid content of TIDCs or altered the ability of TIDCs to prime CD8+ T cells and promote anti-tumor immunity." (PMID 33086073, 2020). "Taken together, these results show that activation of PPARα did not affect the growth of tumor but relieved DOX-induced cardiotoxicity." (PMID 33132907, 2020). "In contrast to these studies, Huang and colleagues did not observe a reduction of tumor vascularization upon PPARα activation with fenofibrate in mice bearing B cell lymphomas." (PMID 32785018, 2020). "First, we observed that DOX significantly reduced the viability of tumor cells in vitro, although the application of the PPARα agonist alone did not affect the viability of tumor cells." (PMID 33132907, 2020). "The effect of PPARα on tumor growth is not entirely clear, and PPARα plays different roles in various types of tumors." (PMID 33132907, 2020). "Our data showed that the activation of PPARα does not promote the growth of these three tumor cells at least, and, interestingly, PPARα activation can improve cardiac dysfunction induced by DOX." (PMID 33132907, 2020). "PPARα regulates genes involved in mitochondrial functions, including FA transport and FAO, and its regulatory effect on CPT1 has been shown to promote oncogenic activity in several tumor tissues." (PMID 30771209, 2019). "Conversely, radiological and histological examination showed that PPARα KD xenografts did not form significant tumour masses in vivo, indicating that GSC lacking PPARα expression have markedly reduced tumour‐initiating capacity." (PMID 30565681, 2019). "Besides,peroxisome proliferators-activated receptors (PPARs, PPARα and PPAR-γ), which inhibit the growth of tumor were also detected." (PMID 31636510, 2019). "Finally, a recent study revealed that peroxisome proliferator-activated receptor alpha (PPARα) upregulated the expression of CPT1C, in a p-53 independent way, modulating proliferation and senescence of tumor cells." (PMID 29445084, 2018). "Consistent with prior reports of the involvement of PPARα activation in promoting M2 macrophages, TPST-1120 skews toward an M1 effector macrophage phenotype and in vivo pretreated peritoneal macrophages enhance the uptake of whole tumor cells by FACS." (PMID 30400835, 2018). "In conclusion, our data support, for the first time, a crucial role of PPARα in regulating the metabolic switch that allows GSCs to survive in O2 and nutrient limitations and demonstrate the effectiveness of GW6471 as anti-tumor and lipid/glucose storage-reducing drug." (PMID 29312541, 2017). "This negative effect of PPARα stimulation during carcinogenesis is directed toward proliferation of endothelial cells, rather than tumor cells, via suppression of epoxyeicosatrienoic acid biosynthesis." (PMID 28316613, 2017). "A study using a mouse xenograft model showed that absence of PPARα expression in the host animals suppresses tumor growth of Lewis lung carcinoma (LLC) cells and lung and liver metastasis of B16 melanoma cells." (PMID 28316613, 2017). "High expression of PPARα, high Karnofsky Performance Status (KPS) score, total tumor resection, and high levels of the proliferation markers, Ki-67, PCNA, P170 and high TOPO II were all associated with overall survival, whereas gender and increasing age were not." (PMID 27835866, 2016). "In fact, the decreased PPARα in tumor specimens compared to non-neoplastic mucosa was supported by our “in vitro” study supporting a direct correlation between PPARα and apoptosis." (PMID 19841681, 2009). "Paradoxically, in spite of the enhanced inflammatoryresponse in the absence of PPARα, tumor growth is suppressed in these animalsas a consequence of an increased production of anti-angiogenic factors TSP-1and endostatin." (PMID 18670614, 2008).
tumor (continued). "Here we show that overt inflammation in the absence of PPARα in the host tissue prevents tumor growth." (PMID 17327920, 2007). "Although these findings suggest that the presence of PPARα both in the tumor cells as well as in the host is necessary for unabated tumor growth, they also demonstrate that PPARα in tumor cells is not necessary for tumor cell viability." (PMID 17327920, 2007). "We used several murine models to determine how the increased inflammatory response observed in the absence of PPARα affects tumor growth and metastasis." (PMID 17327920, 2007). "The reason for the different effects of PPAR ligands, that is, decrease ofcell proliferation in some tumor cells inducing PPARγ, or inductionof apoptosis in others inducing PPARα, is not yet clear." (PMID 17389773, 2007). "Additionally, hsa_circ_0110,102 sponges miR-580-5p to downregulate PPARα and inhibit CCL2 secretion, subsequently suppressing the release of pro-inflammatory cytokines from macrophages via the COX-2/PGE2 pathway, exerting a tumor-suppressive effect." (PMID 41602547, 2026). "Importantly, PPARα-mediated key events (KEs) including hepatocellular hypertrophy and proliferation that have been shown to occur prior to tumor development in this MOA are rodent-specific and likely not human-relevant." (PMID 40216583, 2025). "Whether these differences among the various studies in terms of whether or not HMGCS2 is a tumor suppressor or tumor promoter in the colon can be explained by the expression status of PPARα in the tumor tissue is yet to be investigated." (PMID 40305364, 2025). "However, the reduction in PPARA expression for the tumor datasets was not significantly different from that obtained from the SES datasets." (PMID 39195246, 2024). "Notably, FBP can also inhibit PPARα-mediated FAO, thereby inhibiting tumor development." (PMID 37064872, 2023). "Similar to PPARα/δ agonists, precursors of reactive oxygen species, AMPK activators and mitochondrial uncouplers potentiated the tumoricidal activity of PD1 Abs by expansion of mitochondrial mass and effector/memory cytotoxic T-cells in draining lymph nodes and within the tumor." (PMID 37686465, 2023). "Chronic PPARα activation can lead to a number of toxicities, the most notable of which are increases in hepatocellular adenomas and carcinomas in mice, and increases in tumors in the liver, testis, and pancreas (known as the tumor triad) in rats." (PMID 38133364, 2023). "In addition, PPARα induces fatty acid synthesis by upregulating FAS, and increased FAS expression may indicate tumor aggressiveness and poor prognosis in renal cell carcinoma." (PMID 37251321, 2023). "Therefore, we hypothesized that the PPARA agonist, fenofibrate, could reduce the content of DNMT1 and rescue the expression of methylation-silenced tumor suppressor genes." (PMID 33959155, 2021). "We found that PPARα expression decreased in heart tissues but did not change in the tumor tissues." (PMID 33132907, 2020). "As ligands of peroxisome proliferators-activated receptors (PPAR), AEA, and eicosanoids both activate PPARα, PPARβ/δ, and PPARγ, which bind to peroxisome proliferator hormone response elements (PPREs) of SNAILs, ZEBs or TWISTs to regulate their expression and control tumor metastasis." (PMID 32839493, 2020). "Finally, to further evaluate the therapeutic efficacy of PPARα inhibition combined with immunotherapy, we examined whether GW6471 could enhance the anti-tumor efficacy of a therapeutic vaccine." (PMID 33086073, 2020). "PPARα inhibition had a cytotoxic effect on CLL cells and improved the therapeutic efficacy of glucocorticoid therapy, whereas activation of PPARα with its agonist fenofibrate was shown to suppress tumorigenesis in several studies, possibly due to the triggering of ineffective tumor metabolism." (PMID 30771209, 2019).
tumor (continued). "Once activated, PPARα translocates into the nucleus, and then binds to the PPAR response element (PPRE) in the promotor of the Cyp2c44 gene and reduces its expression, thereby indicating why PPARα agonists inhibit angiogenic activity and tumour vascularization." (PMID 31791289, 2019). "Of note, SCD1 was the most up-regulated molecule involved in both the PPARα pathway and oxidation-reduction process, which suggested that SCD1 might be a key molecule involved in maintaining stem-cell phenotypes of sphere-forming tumor cells." (PMID 31370822, 2019). "In contrast, the growth ofthe same tumor cells is not prevented in WY14643-treated PPARα null mice." (PMID 18725983, 2008). "Therefore, PFOA exposure resulted in some transcriptional responses that were specific for PPARα agonists and distinct from E2; however, they were not correlated with tumor enhancement by DHEA and PFOA." (PMID 18709148, 2008). "However, our model does not exclude a contribution by cell-autonomous tumor promoting effects of PPARα." (PMID 17327920, 2007). "Therefore, PPARα does not simply suppress inflammation, acting in opposition to NF-κB, but it does so in a qualitatively different manner in that cellular infiltrates that do not express PPARα, actively suppress rather than stimulate tumor growth." (PMID 17327920, 2007). "However, we found that the neutralizing TSP-1 antibody did not completely restore tumor growth in PPARα KO mice to the level of that in WT mice, p<0.02." (PMID 17327920, 2007). "The non-growing PPARα(−/−)MEF/RS tumors in PPARα KO mice prompted us to investigate whether these tumors were just a mass of connective tissue or viable dormant microtumors, a state in which tumor cell proliferation is balanced by cell death." (PMID 17327920, 2007). "Therefore, the absence of PPARα in the stromal tissue of the host appears to have two major consequences: an increase in inflammation and a decrease in tumor angiogenesis." (PMID 17327920, 2007). "However, increased PPARα clearly has an indispensable role in enhancing macrophage immune activity in ACE10/10 mice, as proven by gene expression profiles, metabolic characterization, and two different types of immune challenge, tumor and bacterial infection, in this study." (PMID 39910334, 2025). "Moreover, there was no relation of PPARα expression in tumours and tumour grades." (PMID 34572440, 2021). "Mice lacking PPARα had increased expression of DNMT1 and protein arginine methyltransferase 6 (PRMT6), resulting in methylation of the tumour suppressor genes P21 and p27, respectively." (PMID 34638914, 2021). "Our results showed that the expression of PPARα in DOX-treated cardiomyocytes decreased, both in vivo and in vitro, but there was no similar change in tumor tissues." (PMID 33132907, 2020). "In this study, we observed decreased expression of PPARα in the heart of tumor-bearing mice already treated with DOX; however, no such phenomenon was observed in tumor tissues." (PMID 33132907, 2020). "The exact role that PPARα signaling plays in NSCLC and the mechanisms by which PPARα ligands suppress tumor cell growth have not been fully elucidated." (PMID 23867003, 2013). "It is clear that the mechanism of tumor induction by DEHP is not known, and a greater understanding of the interplay between PPARα activation and PPARα-independent Kupffer cell activation is needed." (PMID 18197312, 2008). "Analysis of the small (<2 mm), non-growing lesions at the injection site identified viable PPARα(−/−) MEF/RS large T antigen expressing and proliferating tumor cells." (PMID 17327920, 2007). "These are related to both existing study designs (e.g., a less-than-lifetime analysis of tumor induction) and to whether the intrinsic characteristics of these knockout mice mean that they exhibit responses that differ from those of wild-type mice independent of effects related to PPARα agonism." (PMID 16966106, 2006).
tumor (continued). "However, the exact role that PPARα signaling plays involved in non small cell lung carcinoma (NSCLC) biology and the mechanisms by which PPARα ligands suppress tumor cell growth have not been fully elucidated." (PMID 23867003, 2013). "The lack of tumor enhancement by CLOF is also a novel observation in trout and is supported by data indicating that another potent PP and PPARα agonist, Wy-14,643, does not enhance tumor incidence in trout after chronic exposure postinitiation (Carpenter H, personal communication)." (PMID 18709148, 2008).
metabolic disorders (234 papers, 2008 to 2026). "Studies using hepatic PPARα knockout mice have provided clear evidence that hepatic PPARα deficiency promotes the progression of MASLD-related metabolic disorders." (PMID 40427382, 2025). "For instance, OS causes metabolic disorders by affecting the regulation of PPARα, AMPK/mTOR, and SIRT3/FOXO3a." (PMID 35784531, 2022). "Emerging studies have identified a cardinal role for BVR-A in mitigating susceptibility to metabolic disorders through activation of a PPARα-dependent pathway via regulation of glycogen synthase kinase-3β (GSK3β)." (PMID 35326205, 2022). "PPARα/r dual agonists are also under development to treat more complex metabolic diseases, but some exhibit side effects and cause liver or cardiac dysfunction." (PMID 33496266, 2021). "Polymorphisms of PPARα are of interest in order to improve our understanding of metabolic disorders associated with a raised or reduced risk of diseases." (PMID 31489930, 2019). "Nonetheless, we cannot exclude that it was due to an undetected subclinical state, given that metabolic disorder, for example, is associated with significantly decreased spinal PPARα expression." (PMID 31608295, 2019). "The knowledge of the role of PPARα in metabolic disorder-associated cardiovascular diseases was well recognized in this special issue." (PMID 24782893, 2014). "We demonstrated that allantoin, a terminal oxidation product of UA, not only serves as a biomarker of oxidative stress in individuals with metabolic disorders but also functions as a risk factor that directly promotes MASLD progression by disrupting PPARα regulated TG and TC metabolism." (PMID 40427382, 2025). "The findings of this study suggest that the CGJ-specific compound DPP could be a novel PPARα/γ dual agonist; however, further studies are warranted to examine its therapeutic potential in various metabolic disorders linked with PPARα/γ dysregulation." (PMID 34639224, 2021). "The advantage of dual PPARα/γ agonists is, that they, in addition to the insulin-sensitizing effects of PPARγ, improve lipid parameters and reduce cardiovascular complications associated with metabolic disorders through PPARα." (PMID 31918918, 2020). "The development of MD001 as a PPARα/γ dual agonist targeting metabolic disease may help to overcome the limitations associated with previous PPAR agonists." (PMID 30733541, 2019). "PPARα activation could lower fat accumulation inside macrophages, a major cause for macrophage inflammation and this is directly linked to another important metabolic disorder, atherosclerosis." (PMID 36718668, 2023). "Anti-metabolic disorder therapies targeting PPARα and PPARγ include fibrates, TZDs, and dual agonists." (PMID 40985048, 2025). "Even at environmental concentrations found in drinking water, GenX can disrupt hepatic lipid metabolism by activating the peroxisome proliferator-activated receptor alpha (PPARα) signaling pathway, leading to metabolic disorders." (PMID 40863893, 2025). "The present review summarizes the available data on PPARγ and PPARα regulation via epigenetic mechanisms, elucidating the link between the development of metabolic disorders and the dysregulation of PPARγ and PPARα resulting from these mechanisms." (PMID 39595621, 2024). "This study revealed the hypoglycemic and hepatoprotective effect of CP by regulating gut microbiota composition and PPARα subcellular localization, highlighting its potential for therapeutic candidate for metabolic disorders." (PMID 38831430, 2024). "Our recent studies, alongside numerous others, have highlighted the pivotal roles of DNA methylation and histone modifications in the regulation of PPARγ and PPARα, implicating them in the deterioration of metabolic disorders via epigenetic mechanisms." (PMID 39595621, 2024).